EPX (eosinophil peroxidase)
Description:
Heme-containing oxidoreductase that catalyzes the oxidation of small anions, such as nitrite, halides (e.g bromide and chloride (at pH 6.5)) and pseudohalides (e.g thiocyanate) by using hydrogen peroxide to generate the corresponding reactive species hypobromite, hypochlorite, hypothiocyanous acid, and nitrogen dioxide. Also oxidizes thiocyanate (SCN(-)) to cyanate (OCN(-)). Functionally involved in inflammatory responses and exhibits antimicrobial activity. Can also oxidize amino acid residues on proteins and generate bromination, nitration and carbamoylation post-translational modifications, respectively. Mediates the nitration of tyrosine (3-nitrotyrosine) which is only observed in secondary granule proteins in mature resting eosinophils in the presence of the cosubstrates, hydrogen peroxide and nitrite. Mediates oxidation of tyrosine residues on proteins in eosinophils to form brominating species, 3-bromotyrosine and 3, 5-dibromotyrosine in the presence of hydrogen peroxide and bromide (By similarity). Promotes protein carbamoylation at sites of inflammation during asthma by using thiocyanate and hydrogen peroxide to form cyanate which carbamoylates lysine residues to form homocitrulline.
Synonyms: EPO; EPP; EPX-PEN; EPXD
Tractability: Small molecule: a high-quality ligand is known; it belongs to a druggable protein family. Antibody: its Gene Ontology location is reachable by antibodies, with high confidence; UniProt predicts a signal peptide or a membrane-spanning region. PROTAC: a small molecule that binds it is known.
Target class: Enzyme; Oxidoreductase
Gene: Protein-coding gene on chromosome 17 (58,192,726 to 58,205,174, forward strand). Ensembl gene ENSG00000121053.
Subcellular location: Cytoplasmic granule
Pathways (Reactome):
Immune System: Neutrophil degranulation
Gene Ontology:
Molecular function: lactoperoxidase activity; peroxidase activity; heme binding; thiocyanate peroxidase activity
Biological process: antibacterial innate immune response; inflammatory response; defense response to bacterium; cellular oxidant detoxification; response to oxidative stress; thiocyanate metabolic process
Cellular component: extracellular exosome; extracellular region; secretory granule lumen
Genetic constraint (gnomAD): Loss-of-function variants: 55 observed, 69.94 expected, observed/expected ratio (o/e) 0.79, 90% interval 0.63 to 0.98. The upper end of that interval is the gene's LOEUF score, 0.98, which puts it in group 4 of 6, group 1 being the genes least tolerant of losing a copy. Missense variants: 942 observed, 1,006.2 expected, observed/expected ratio (o/e) 0.94, 90% interval 0.89 to 0.99. Synonymous variants: 346 observed, 405.73 expected, observed/expected ratio (o/e) 0.85, 90% interval 0.78 to 0.93.
Homologues: Orthologues: chimpanzee EPX (99% identical), macaque EPX (97% identical), rabbit EPX (90% identical), mouse Epx (89% identical), guinea pig EPX (89% identical), rat Epx (89% identical), dog EPX (88% identical), pig EPX (84% identical), tropical clawed frog epx (58% identical), tropical clawed frog mpo (54% identical), zebrafish mpx (49% identical), Drosophila melanogaster Pxn (37% identical), and 7 more. Paralogues in human: MPO (70% identical), LPO (52% identical), TPO (45% identical), PXDN (41% identical), PXDNL (39% identical).
Diseases named in the same sentence as EPX in open-access papers:
EPX is named in the same sentence as 64 diseases in open-access papers, as found by Europe PMC text mining. Sharing a sentence is not in itself a finding about the gene and the disease. The quoted sentences say what the papers report.
asthma (48 papers, 2007 to 2025). "Activated eosinophils release eosinophil peroxidase, which causes oxidative damage in patients with asthma." (PMID 35887041, 2022). "Discovered DMRs annotated to genes implicated in allergy and asthma, Th2 activation and eosinophilia (EPX, IL4, IL13, PRG2, CLC and ZFMP1) and genes previously associated with asthma and IgE in an EWAS of blood (ACOT7, SLC25A25)." (PMID 35344303, 2022). "Other studies have reported the derivate of L-tyrosine, bromotyrosine, to be associated with asthma, which is plausible as bromotyrosine results from eosinophil activation via eosinophil peroxidase during inflammatory responses." (PMID 33339279, 2020). "In this external cohort’s findings for atopic asthma, we identified 61% (48/79) of CpGs that replicated (FDR < 0.05 for 48 comparisons), all with consistent direction of association including multiple CpGs annotated to EVL and EPX genes for our asthma results." (PMID 31300640, 2019). "Overall, our findings indicate that eosinophilic airway inflammation is an important cause of bronchiectasis in severe asthma, and support that this is related to an increased activation of airway eosinophils, with degranulation with release of cytotoxic enzymes such as EPX." (PMID 37780108, 2023). "Pathological changes in asthma are caused by the activation of structural lung cells and airway remodeling, which contain enzymes such as eosinophil cationic protein, eosinophil peroxidase, or major basic proteins that cause epithelial damage (a hallmark of asthma)." (PMID 36726968, 2022). "Because eosinophilic inflammation — eosinophil counts and levels of eosinophil peroxidase (EPX) in blood and sputum — are known to be linked to mucus plug segment scores in asthma, we explored whether the size of individual mucus plugs was influenced by eosinophilic inflammation." (PMID 38127464, 2024). "The relevance between the FEO‐03 network and asthma on the KEGG Pathways database presented EPX, IL4, IL5, IL13, CD40LG, TNF, and IL10 according to p value." (PMID 40777200, 2025). "Quercetin significantly suppressed eosinophil peroxidase activity, tissue migration and bronchial remodeling induced by asthma." (PMID 41357894, 2025). "The IMC analyses identified that immune cells infiltrating mucus plugs from patients with asthma predominantly coexpressed EPX and ELA2." (PMID 40091838, 2025). "In characterizing the cellular features of the mucus plug themselves in asthma, we found that the predominant infiltrating cells were granulocytes that were frequently dual positive for eosinophil peroxidase and neutrophil elastase." (PMID 40091838, 2025). "Asthma mucus plugs were infiltrated with immune cells that were mostly dual positive for eosinophil peroxidase (EPX) and neutrophil elastase, suggesting that neutrophils internalize EPX from degranulating eosinophils." (PMID 40091838, 2025). "Eosinophilic mucin, which is formulated in the presence of eosinophilic peroxidase (EPX), is a predictor for disease severity in ECRS and associated with chronic airway obstruction in severe asthma." (PMID 38067174, 2023). "A small study showed high levels of both ECP and eosinophil peroxidase as predictive for the future development of asthma among those with allergic rhinitis." (PMID 37186426, 2023). "In the lungs of patients with asthma, eosinophil infiltration will release eosinophil peroxidase (ECP)." (PMID 35565807, 2022). "In a guinea pig model of asthma, genistein significantly inhibited ovalbumin-induced acute bronchoconstriction, reduced pulmonary eosinophilia and eosinophil peroxidase activity." (PMID 34684599, 2021). "Treatment with the extract of Z. multiflora and its constituent, carvacrol also improved total and differential WBC, IgE and eosinophil peroxidase levels as well as lung pathology in an animal model of asthma." (PMID 32995329, 2020).
asthma (continued). "Functional gene categories represented in DMRs and individual CpGs found for FeNO, asthma, and allergy were eosinophilic activity (EPX, CLC, PRG2), and Th2 responses (IL-4, ZFPM1)." (PMID 31300640, 2019). "Discovered DMRs annotated to genes implicated in allergic asthma, Th2 activation and eosinophilia (EPX, IL4, IL13) and genes previously associated with asthma and IgE in EWAS of blood (ACOT7, SLC25A25)." (PMID 31300640, 2019). "It is known that eosinophil recruitment and presence of granular proteins such as major basic protein, eosinophil cationic protein, or eosinophil peroxidase are biomarkers for monitoring allergic inflammatory disorders, such as asthma." (PMID 31632296, 2019). "In analyses of asthma and allergy, we observed lower DNAm of several CpGs in genes regulating eosinophilic and Th2 responses: EPX and IL-4, respectively." (PMID 31300640, 2019). "Many of the methylation sites we identified have been associated with asthma including ADAM19, EPX, IL4, IL5RA, and PRG2." (PMID 29692868, 2018). "Several of these methylation loci were previously associated with asthma (ADAM19, EPX, IL4, IL5RA, and PRG2)." (PMID 29692868, 2018). "Specifically, we identified multiple methylation loci in genes previously associated with asthma (ADAM19, EPX, IL4, IL5RA, and PRG2) from genome-wide and epigenome-wide association studies." (PMID 29692868, 2018). "This gene set includes numerous cytokines that mediate Th2 cell signaling associated with asthma (IL3, IL4, IL5, IL9, IL10 and IL13), as well as components of the IgE receptor (FCERA, FCERG, MS4A2) and eosinophil granule proteins (ECP, EDN, EPX, and MBP)." (PMID 28854632, 2017). "The functional annotation results implicated the genes EPX and PRG2 in eosinophil activity and in the KEGG pathway for late hypersensitive responses in asthma." (PMID 26292806, 2015). "The most interesting of these findings involved two genes (EPX and PRG2) in the KEGG pathway for asthma (Benjamini P-value = 0.00056) and associated with the eosinophils annotation (Benjamini P-value = 0.0087)." (PMID 26292806, 2015). "Although not used as widespread as other T2 high biomarkers, sputum EPX and anti-EPX autoantibodies may prove useful for severe asthma endotyping and biologic therapy in the future." (PMID 40863432, 2025). "Eosinophil peroxidase is a valid biomarker of eosinophilic inflammation in asthma, and its measurement reveals how blood measures of eosinophilic inflammation can miss airway eosinophilic inflammation and how mepolizumab does not always normalize airway eosinophilic inflammation." (PMID 38663815, 2024). "We measured Sp-IgG and its five subtypes against eosinophil inflammatory proteins (Sp-IgGEPs), including eosinophil peroxidase, eosinophil major basic protein, eosinophil-derived neurotoxin, eosinophil cationic protein, and Charcot-Leyden Crystal protein in varying asthma severity." (PMID 39091502, 2024). "In considering the limitations of our work, we note that the levels of EPX that are measured in sputum reflect protein that is present in airway secretions because of the secretion by eosinophils activated because of asthma pathobiology and because of the sputum processing procedures." (PMID 38663815, 2024). "Interestingly, recent research has reported autoantibodies to eosinophil peroxidase (EPX), an enzyme closely related to myeloperoxidase, in severe asthma sputum." (PMID 37334358, 2023). "Some patients with severe asthma have autoantibodies against eosinophil peroxidase (EPX) and autologous cellular components in the sputum, which may necessitate an increase for the maintenance of corticosteroids." (PMID 35757774, 2022). "Eosinophil peroxidase (EPX) is released from activated eosinophils, and can be used as a diagnostic and dynamic asthma marker, since its levels are elevated in sputum, nasal, and pharyngeal swabs of patients with uncontrolled asthma and are reduced after anti-eosinophilic therapy." (PMID 34070316, 2021).
asthma (continued). "PF4 and EPX are known to directly contribute to the induction of AHR in asthma models." (PMID 34256766, 2021). "Quercetin as an antiasthmatic, immunomodulatory, and bronchodilatory agent has induced a relaxation effect in tracheal rings and reduced the inflammatory cytokines and eosinophil peroxidase in the lungs according to one in vivo study in a murine model of asthma." (PMID 34335237, 2021). "Specifically, cg10159529 (IL5RA) and cg27469152 in the 3′UTR region of the EPX gene were highly significant in the asthma analysis and in our comparisons of ADEH+ patients versus healthy controls (FDR-adjusted q-value < 0.05) when not adjusting for eosinophils." (PMID 31443688, 2019). "Although curcumin is known for its low systemic bioavailability and is rapidly metabolized in the gut, intranasal delivery in a murine model of asthma reduced airways inflammation, histamine release, and eosinophil peroxidase activity in bronchoalveolar lavage fluid." (PMID 26922672, 2016). "Our finding that serum EPX levels correlate very well with blood eosinophils in cross-sectional analyses at multiple time points is important because it provides supporting evidence that serum EPX is a valid surrogate for measures of blood eosinophil counts in asthma." (PMID 38663815, 2024). "In patients with severe asthma with increased airway degranulation evident by the presence of free eosinophil granules, autoantibodies to eosinophil granule proteins such as eosinophil peroxidase (EPX) and anti-nuclear/extranuclear antigens (ANAs) have been reported." (PMID 39554494, 2024). "The presence of eosinophil granular substances, including MBP, EPX, ECP, and EDN, in the sputum of asthma patients, is believed to be a sign of the degree of their illness." (PMID 39679991, 2024). "The relative utility of eosinophil peroxidase (EPX) and blood and sputum eosinophil counts as disease biomarkers in asthma is uncertain." (PMID 38663815, 2024). "In particular, they observed significant sites in EPX (eosinophil peroxidase) and EVL (Enah/Vasp-like) genes for asthma." (PMID 32500051, 2020). "Studies on EOXs role in the pathology of asthma have revealed that the composition of EOXs in patients with asthma and healthy individuals are similar in size and carries important enzymes such as EPO (Eosinophil peroxidase), MBP (Major basic protein), and ECP (Eosinophil cationic protein)." (PMID 35550636, 2022). "Mice lacking Rab27a, which is highly expressed and activated in asthma, had reduced EPX release in BAL fluid, again supporting roles of GTPases in Eos exocytosis and degranulation." (PMID 33494375, 2021). "As one of the mechanisms for PP2A hyperphosphorylation in eosinophilic airway inflammation, we confirmed that PTP-RR, a regulator of PP2A-Tyr307 phosphorylation, was reduced under stimulation with EPX and in nasal epithelial cells from ECRS patients with severe asthma." (PMID 32085629, 2020). "These include chemokines, lipid mediators, and cytotoxic granule proteins such as major basic protein (MBP), eosinophil peroxidase (EPX), eosinophil cationic protein (ECP), and eosinophil-derived neurotoxin (EDN), which together result in several key features of asthma." (PMID 29854739, 2018). "Several differentially methylated CpG sites in the EWAS of current asthma at 7.5 years were located in genes that have known links to both eosinophil functions and allergic sensitisation, such as cg27469152 in the 3′UTR region of the EPX gene." (PMID 29046734, 2017). "Another small study comparing fixed-dose oral mepolizumab with weight-based intravenous reslizumab showed greater improvements in airway eosinophilia and asthma control, with the notable observation that four of six mepolizumab non-responders had anti-EPX autoantibodies." (PMID 40863432, 2025).
asthma (continued). "Experimentally induced asthma in a transgenic murine model of sickle cell disease caused greater mortality due to increased allergic lung inflammation (elevations in eosinophils, eosinophil peroxidase, and IgE levels) compared with control sickle cell disease mice without induced asthma." (PMID 21490765, 2011).
eosinophilia (13 papers, 2011 to 2024). "Eosinophils have cytotoxic functions such as releasing major basic protein, eosinophil peroxidase, the eosinophilic cationic protein that causes tissue damage and eosinophilia increases the likelihood of recurrent disease." (PMID 32001208, 2021). "We found that FSHD-like expression of DUX4 is associated with muscle eosinophilia and elevated levels of eotaxin and eosinophil peroxidase, which may serve as new muscle biomarkers for FSHD pathology." (PMID 38340007, 2024). "We demonstrate that these FSHD-like muscles are enriched with the chemoattractant eotaxin and the cytotoxic eosinophil peroxidase, and exhibit muscle eosinophilia." (PMID 38340007, 2024). "Further research is necessary to identify the triggers for eosinophilia in L-HES and the application of the novel monoclonal antibody directed against eosinophil peroxidase to detect eosinophil activity in the airway." (PMID 21362188, 2011). "We identified muscle eosinophilia as a new immune-related marker of FSHD pathology and demonstrate that muscle eosinophilia correlates with an increase in the expression of eotaxin and EPX in muscle." (PMID 38340007, 2024). "Whether or not the patient was on definitive treatment (with a biologic or steroid-sparing immunosuppressant) did not appear to have major impact on anti-TREM1 and anti-EPX serology, and neither did presence/absence of current blood eosinophilia." (PMID 37334358, 2023).
colitis (8 papers, 2015 to 2025). Inflammation of the colon. "In a mouse colitis model, eosinophil peroxidase was shown to contribute to tissue damage (EPO-deficient mice had less colitis), reinforcing that EPX can actively drive inflammation." (PMID 40860650, 2025). "The results showed that cucurbitacin IIb alleviated colitis symptoms including body weight loss, an increase in the disease activity index, and elevated levels of myeloperoxidase and eosinophil peroxidase content." (PMID 39347394, 2024). "GM-CSF increases the production and activity of eosinophils, which are thought to cause tissue damage in colitis through eosinophil peroxidase." (PMID 37373318, 2023). "Since murine experimental colitis induced by Helicobacter hepaticus and IL-10R blockade improve with the chemical inhibition of eosinophil peroxidase, targeting it could be a promising area for future development." (PMID 37373318, 2023). "The results showed that serine decreased the disease activity index, as well as myeloperoxidase, eosinophil peroxidase, and proinflammatory cytokine concentrations in colonic tissue, while serine improved colonic morphology and inhibited cell apoptosis in colitis mice." (PMID 30619148, 2018). "In addition to TNF secretion, release of eosinophil peroxidase promoted colitis identifying direct tissue-toxic mechanisms." (PMID 26200014, 2015). "In a rat model of AA-induced colitis, phloretin, administered orally either before or after induction of colitis (50 mg/kg), effectively reduced plasma ALP and LDH levels, inflammatory markers (MPO, NO, eosinophil peroxidase), and colon ICAM-1 gene expression." (PMID 39494333, 2024). "In addition, healthy donor (HD) bacteria significantly reduced the levels of inflammatory markers Myeloperoxidase (MPO) and Eosinophil peroxidase (EPO), and various pro-inflammatory factors, in colitis mice, and increased the secretion of the anti-inflammatory factor IL-10." (PMID 35237276, 2022).